MIF (macrophage migration inhibitory factor)
Diseases named in the same sentence as MIF in open-access papers (continued):
Sharing a sentence is not in itself a finding about the gene and the disease.
infection (continued). "Studies in MIF-KO mice have additionally shown increased susceptibility to infection with Salmonella typhimurium, Toxoplasma gondii, and Trypanasoma cruzi in the absence of MIF." (PMID 32244916, 2020). "DENV2 infection induced the first wave of MIF secretion at 3–6 h post-infection." (PMID 32545679, 2020). "In contrast, MIF expression may be detrimental during infection with certain viruses and extracellular bacteria." (PMID 32244916, 2020). "Macrophage migration inhibitory factor (MIF) is a pro-inflammatory cytokine that mediates the host response to infection and stress by activating innate and adaptive immune pathways and in particular promotes Th1 immunity, which is a key element of AIH pathophysiology." (PMID 31616649, 2019). "E. histolyica MIF plays an essential role in neutrophil infiltration during infection." (PMID 31497025, 2019). "In addition, ERK 1/2 and PGE2 were able to upregulate T. gondii replication in BeWo cells, demonstrating the beneficial effect of low doses of MIF and its intracellular pathway during infection by Toxoplasma in human villous trophoblast cells." (PMID 31068920, 2019). "Chicken macrophage migration inhibitory factor was secreted upon vvIBDV infection of DT40 and bursal cells; therefore, we investigated whether the supernatant of infected cells could promote PBMC migration." (PMID 31632367, 2019). "Thus, vvIBDV infection both promoted the transcription and increased the protein levels of the host MIF in vivo." (PMID 31632367, 2019). "Additionally, the vvIBDV infection triggered MIF in vivo earlier than the upregulation of IL-1β/IL-18 transcription." (PMID 31632367, 2019). "Notably, infection with serovar D only elicited production of G-CSF and intriguingly MIF and IP-10 were repressed." (PMID 32039039, 2019). "The role of host MIF during parasite infections has been well-reviewed elsewhere." (PMID 31497025, 2019). "Thus, the pregnancy outcome was less damaging for MIF-/- mice compared with WT ones, considering 8 days of pregnancy/infection." (PMID 29867817, 2018). "At day 11 (peak infection), cells were treated with different MIF concentrations." (PMID 29997630, 2018). "We also explored whether CD4+ T-cell viability and infection percentages were affected by the addition of supernatants derived from MDMs treated under the different MIF conditions." (PMID 29997630, 2018). "Endothelial MIF expression was enhanced by P. gingivalis ATCC 33277 infection." (PMID 29482504, 2018). "Moreover, the conditioned environment generated by MIF/CD74 interaction in infected MDMs promotes CD4+ T-cell permissiveness to infection." (PMID 29997630, 2018). "Several lines of evidence suggest that this might be the case, based on the fact that CD74 expression is modulated in HIV-infected cells and that MIF plasma levels are elevated throughout the course of infection in HIV-infected subjects." (PMID 29997630, 2018). "These mortality data agree with a previous study that demonstrated the role of MIF in the resistance of non-pregnant BALB/c mice to T. gondii infection, since BALB/c MIF-/- mice presented a higher mortality rate than their WT counterparts in response to oral infection." (PMID 29867817, 2018). "If activated already in the peripheral phase of the infection, MIF signaling route could favor TBEV invasion into CNS by initiating an early increase in BBB permeability, in analogy with the animal models of WNV encephalitis." (PMID 28646884, 2017). "In addition, MIF has a critical role during infection by many parasites, including Leishmania major and T. cruzi, and there have been previous studies emphasizing its importance against T. gondii infection in maternal-fetal interface." (PMID 28798905, 2017). "Furthermore, we previously showed that BeWo cells treated with MIF or IL-6 recombinant cytokines significantly reduced the T. gondii proliferation, evidencing the important role of these mediators in the control of infection during a pregnancy." (PMID 28798905, 2017).
infection (continued). "Therefore, the present study aimed to assess the role of MIF in the maturation of conventional CD8α+ and CD11b+ DCs during the acute infection with avirulent T. gondii ME49 strain." (PMID 27057101, 2016). "In addition, MIF induced IFN-γ-producing NK cells during the acute phase of infection with T. gondii, required for differentiation of inflammatory monocytes into TipDCs." (PMID 27057101, 2016). "Although MIF plays a critical role in the resistance to T. gondii infection, it is not known whether this protective role starts during the acute phase of infection with the parasite." (PMID 27057101, 2016). "In this context, the role of MIF in regulating NK cell-derived IFN-γ at the site of infection with T. gondii could be essential for the differentiation of Ly6Chigh monocytes into TipDCs." (PMID 27057101, 2016). "Furthermore, there was overexpression of proinflammatory MIF in L. m.-infected BMDM in the late infection phase." (PMID 26226952, 2015). "MIF plays an essential role in the pro- and anti-inflammatory response to infection." (PMID 27065766, 2015). "It is known that MIF is involved in the replication of many different viruses during infection." (PMID 25821355, 2015). "During severe infection, MIF accumulates both in the parenchymal tissue and in the alveolar spaces." (PMID 26318747, 2015). "Macrophage migration inhibitory factor (MIF) has an important role in controlling infection." (PMID 27065766, 2015). "Accordingly, liver MIF protein levels increased drastically during the chronic phase of infection." (PMID 25255103, 2014). "The expression levels of interleukins (IL-6 and IL-8), chemokines (MCP-1, MIF and GROα) and growth factors (G-CSF and GM-CSF) increased steadily from 8 h until 24 h post infection whereas the parasite burden decreased erratically until 24 h post infection." (PMID 24886982, 2014). "Chemokines: MCP-1, MIF, GROα and Rantes reached peak levels significantly at 8 h post infection." (PMID 24886982, 2014). "The more sustained MIF production during the chronic stage of infection compared to the acute stage could also account for the observed accumulation of inflammatory monocytes in WT infected mice." (PMID 25255103, 2014). "The higher TNF and IFN-γ response observed in WT mice compared to Mif−/− mice during the chronic stage of infection could result from the reported positive feedback loop between MIF, TNF and IFN-γ." (PMID 25255103, 2014). "However, to fully validate the role of MIF in chagasic infection a complete inhibition of its expression in infected cells (cardiomyocytes, macrophages and fibroblasts) should be achieved." (PMID 23451183, 2013). "To further confirm the results of the ELISA analysis, we conducted an RT-PCR to examine whether the effect of DV2-infection-induced MIF production is dose-dependent in HUVECs." (PMID 23383040, 2013). "FREP 2 and 3, coagulation factor IX, dermatopontin, dual oxidase, galectin 4, MIF, peroxiredoxin, superoxide dismutase Cu-Zn, and heat-shock protein 70 all exhibited increased expression in snails that successfully resisted infection compared to those that were infected by S. mansoni." (PMID 22479663, 2012). "The fact that anti-MIF only has a minor impact on the immune response to B. pseudomallei could be related to differences in the primary site of infection and/or differences in the pathogens involved." (PMID 20169062, 2010). "While this could be important in the resting state, the strong impact MIF has on induction of inflammation in response to infection suggests a different role for this molecule during active infection." (PMID 20361053, 2010). "Furthermore, mice with melioidosis that were treated with a MIF blocking treatment showed lower bacterial counts in their lungs during infection." (PMID 20169062, 2010). "To evaluate whether anti-MIF treatment interferes with bacterial clearance, we first determined bacterial loads 48 hours after infection with an inoculum of 2.5×102 CFU B. pseudomallei." (PMID 20169062, 2010).
infection (continued). "Similarly, Plasmodium MIF is thought to influence the host immune response and the course of anemia during infection." (PMID 20886098, 2010). "At 24 h after onset of infection there were modest but significantly (P = 0.04) lower bacterial levels in both the extracellular and intracellular samples from the corneas of the infected MIF KO mice when compared to C57Bl6 control animals." (PMID 20361053, 2010). "Serum MIF peaked 9 h post-infection and then declined; IL-6 and TNF-α continuously increased." (PMID 20939898, 2010). "Our results uncover a host factor that elevates inflammation and propagates bacterial cellular invasion, and further suggest that inhibition of MIF during infection may have a beneficial therapeutic effect." (PMID 20361053, 2010). "Functional analysis of these sequences may be of considerable interest, given that MIF expression in the filarial worm Brugia malayi influences the progression of the CD4+ T cell response to infection towards a TH2 pathway." (PMID 17645880, 2007). "Furthermore, MIF plays a crucial role in regulating macrophage responses during infection." (PMID 41159021, 2025). "MIF signaling maintains the production of cytokines and macrophage activation, which increases pro‐inflammatory responses and may increase immune‐driven tissue damage in severe infections." (PMID 40910395, 2025). "However, elevated MIF at the healthiest point may stem from factors like infection, glucocorticoid use, and trauma." (PMID 38650940, 2024). "Therefore, we hypothesized that the occurrence of infection in MN patients was correlated with the MIF levels, and we analyzed the correlation of plasma and urinary MIF levels in MN patients with infection-related clinical indicators." (PMID 36329091, 2022). "Therefore, this review aims at summarizing the current knowledge on the roles of MIF and IL-10, which can be considered as a molecular “Yin-Yang” in the modulation of the host immune microenvironment during infection, and particularly during African trypanosomosis." (PMID 35464430, 2022). "The degree of infection, microbial count, and host immune responses showed more potential as factors than age, which may have obscured the impact of age on the levels of serum MIF." (PMID 35237527, 2021). "In this respect, we have reported before that MIF plays a key role in T. congolense infection associated pathogenicity and we demonstrated here that MIF levels were significantly upregulated in TgAlbCre-IL10-/- mice during later stages of infection both systemically and in the liver." (PMID 32012211, 2020). "Thus, MIF seems to play an important, protective role in infection control." (PMID 33238656, 2020). "Because Leishmania MIF appears to play a role in reducing long-term immunity, immunization with the cytokine could prove a successful strategy for inducing protection to initial and recurrent infection." (PMID 32244916, 2020). "Similarly, DENV2 infection of HuH-7 cells can drive two waves of MIF secretion." (PMID 32545679, 2020). "In an ex vivo whole blood infection, tempol treatment reduced C. albicans colony forming units and at the same time increased the release of pro-inflammatory cytokines, such as interleukin 8 (IL-8, monocyte chemoattractant protein-1, and macrophage migration inhibitory factor)." (PMID 31481939, 2019). "Similarly, unactivated CD4+ T-cells sensitized with supernatants from infected MDMs treated with 25 ng/ml MIF showed a significant, albeit transient, increase in viral production at day 4 post-infection, compared to the uninfected condition, which was later downmodulated." (PMID 29997630, 2018). "Additionally, MIF plays an important role in the host defense against infection by parasites." (PMID 29867817, 2018).
infection (continued). "MIF plays an important role in the pathogenesis of immune diseases by inhibiting the migration of macrophage, and promote the aggregation, invasion, proliferation, activation, and secretion of several cytokines of the macrophage at the site of infection to produce a strong immune response." (PMID 29773680, 2018). "As MIF/D-DT shRNA expressing cells appeared to have significantly fewer viable cells compared to the nonsense control following infection/selection, we next evaluated whether there was any appreciable effect on cell survival following depletion of MIF and D-DT." (PMID 24932684, 2014). "Thus, it appears that one host molecule makes a major contribution to both aspects of disease resulting from P. aeruginosa corneal infection, indicating a high potential for ameliorating the consequences of this infection by therapies that target the activities of MIF." (PMID 20361053, 2010). "Thus, it appears in the basal state MIF limits cellular activation, but a consequence of this is that the responses to infection are dampened and the increased infiltration of PMN into the infected cornea that is needed to deal with the increased bacterial burdens results in more tissue pathology." (PMID 20361053, 2010). "Doses of 25–100 mg/kg baicalin also increased the mRNA expression levels of MIF and CD74 in the spleen compared to the infection group (p < 0.05)." (PMID 40427533, 2025). "Interaction between CD74 and MIF enhances the secretion of proinflammatory mediators and promotes unactivated CD4+ T cell infection, leading to viral spreading." (PMID 40427533, 2025). "The results demonstrated that untreated A549 cells infected with B. pseudomallei expressed significantly higher amounts of MIF, PAI-1, IL-18, CXCL1, CXCL12 and IL-8 when compared with uninfected cells at 12 h post-infection." (PMID 36758060, 2023). "Macrophage migration inhibitory factor (MIF) is a pro-inflammatory factor needed to control T. gondii infection, playing a pivotal role in the control of the infection particularly during gestation." (PMID 36968102, 2023). "MIF also induces the targeted migration of T cells via CXCR4, and is thus involved in the adaptive immune response to infections." (PMID 38275363, 2023). "MSCs stimulated by bacterial lipopolysaccharide (LPS) can enhance antimicrobial functions of neutrophils, IL-8, and macrophage migration inhibitory factor (MIF), thus aiding the resolution of inflammation and infection." (PMID 35741711, 2022). "This study revealed interesting changes in the gut microbiota of MIF KO and WT C57BL/6 mice before and after PbA infection." (PMID 36033889, 2022). "Leptospiral LPS triggered the upregulation of MIF expression at 24 h post-infection, which reached the peak level at 24 h post-treatment in THP-1 cells and showed elevated MIF expressions in different tissues of BALB/c mice at the early stage of infection." (PMID 35237527, 2021). "The expressions of MIF, XCL1 and CXCL12 decreased at the early stage of infection, indicating IBV affects macrophage chemotaxis." (PMID 33509253, 2021). "Yet, between 38–48 days post infection, all tested pro-inflammatory cytokines (IFN-γ, TNF, IL-6 and MIF) increased or remained high in TgAlbCre-IL10-/- mice, but not in the other strains." (PMID 32012211, 2020). "This corresponded with increased parasite burden in mice infected with wildtype versus mif-/- L. major late in infection, suggesting a reduction in the formation of long-lived effector CD4 T cells in the presence of Leishmania MIF." (PMID 32244916, 2020). "Macrophage migration inhibitory factor (MIF) is a proinflammatory cytokine mainly released from Th2 cells and macrophages, which can mediate the host response to infection and stress by activating innate and adaptive immune pathways." (PMID 32410863, 2020).
infection (continued). "Cytokines GM-CSF, GRO-α, I-309, IL-1β, IL-6, MCP-1, MCP-2, TNF-α, thrombopoietin, BLC, Flt-3 ligand, HGF, IP-10, MIF, and MIP-3α were elevated by ≥1.5 fold relative to mock infection in both independent biological replicates of the cytokine array." (PMID 31536604, 2019). "Cytokines that are upregulated during acute human infection include IL-6, IL-16, IL-17, IP-10, MCP-1, MIF, stromal cell-derived factor-1α, IL-1rα, IL-2rα, G-CSF, GM-CSF, VEGF, IL-7, IL-12p40, and IFN-α2." (PMID 31053842, 2019). "Interestingly, the association to the polymorphism with infectious diseases suggests that MIF expression may not be part of an effective immune response against infection." (PMID 29545822, 2018). "An earlier study by our group, using human placental explants, demonstrated that MIF and its receptor (CD74) were upregulated in response to T. gondii infection, thus playing an important role in controlling infection in a gestational age-dependent manner." (PMID 29867817, 2018). "The MIF inhibitor ISO-1 inhibited ICAM-1 production in endothelial cells, and monocyte-endothelial cell adhesion was induced by P. gingivalis ATCC 33277 infection." (PMID 29482504, 2018). "In addition, the secretion of MIF at the site of infection by the helminths, which might induce production of endogenous host MIF, may lead to blockade of AP-1-dependent proinflammatory gene expression by binding the transcription factor Jun activation domain-binding protein 1 (Jab1)." (PMID 28402951, 2017). "However, MIF-overexpressing macrophages might be potentially involved in the enhancement of Leishmania infection in vivo by recruiting new uninfected host macrophages to the infection." (PMID 26226952, 2015). "At 8 h post infection with PRU, IL-6, IL-8, MIF, MCP-1 synthesis and parasite levels peaked, when GROα and Rantes synthesis remained low." (PMID 24886982, 2014). "Infection or stimulation of chorionic explants with molecules of T. gondii, IFN-γ, and IL-12 evoked the secretion of MIF." (PMID 22496958, 2012). "Integrated proteomic and in silico molecular docking analyses revealed favorable binding between punicalagin and several key innate immune proteins upregulated during infection, including Toll‐like receptor 2 (TLR2), its adaptor MyD88, and the cytokine macrophage migration inhibitory factor (MIF)." (PMID 41085014, 2026). "When MIF binds to CXCR2, it triggers chemotactic responses, driving the recruitment and migration of immune cells, such as monocytes and neutrophils, to sites of inflammation, potentially contributing to the early immune response against infections." (PMID 41159021, 2025). "When the piglets were infected with G. parasuis, the mRNA expression levels of MIF and CD74 in the spleen were significantly reduced (p < 0.001), while levamisole enhanced the MIF and CD74 mRNA levels in the spleen compared to the infection group (p < 0.01)." (PMID 40427533, 2025). "Similarly, MIF interaction with CXCR4 promotes the directed migration of T cells, playing a role in the adaptive immune response to infections." (PMID 41159021, 2025). "Additionally, pro-inflammatory cytokines, including MIF, PAI-1, IL-18, CXCL1, CXCL12 and IL-8, were statistically decreased (P < 0.05) in 10−6 M 1α,25(OH)2D3-pretreated A549 cells by 12 h post-infection." (PMID 36758060, 2023). "MIF has for example been shown to play a pivotal role in immunity against Salmonella typhimurium, as Mif -/- mice failed to control infection due to an impaired TH1 response." (PMID 35464430, 2022). "MIF can then be directly secreted in response to various stimuli such as infection and cytokine stimulation, which if not properly controlled can cause cell and tissue injury." (PMID 35464430, 2022). "It has been demonstrated that MIF plays a critical protective role during acute T. cruzi infection, by inducing the production of several pro-inflammatory cytokines, including IL-12, IL-18, TNF, IL-1β, and IFNγ, during the early phase of infection." (PMID 35464430, 2022).